THOC5 (THO complex subunit 5)
Description:
Component of the THO subcomplex of the TREX complex which is thought to couple mRNA transcription, processing and nuclear export, and which specifically associates with spliced mRNA and not with unspliced pre-mRNA. Plays a key structural role in the oligomerization of the THO-DDX39B complex. TREX is recruited to spliced mRNAs by a transcription-independent mechanism, binds to mRNA upstream of the exon-junction complex (EJC) and is recruited in a splicing- and cap-dependent manner to a region near the 5' end of the mRNA where it functions in mRNA export to the cytoplasm via the TAP/NXF1 pathway. THOC5 in conjunction with ALYREF/THOC4 functions in NXF1-NXT1 mediated nuclear export of HSP70 mRNA; both proteins enhance the RNA binding activity of NXF1 and are required for NXF1 localization to the nuclear rim. Involved in transcription elongation and genome stability. Involved in alternative polyadenylation site choice by recruiting CPSF6 to 5' region of target genes; probably mediates association of the TREX and CFIm complexes. Regulates the expression of myeloid transcription factors CEBPA, CEBPB and GAB2 by enhancing the levels of phosphatidylinositol 3,4,5-trisphosphate. May be involved in the differentiation of granulocytes and adipocytes. Essential for hematopoietic primitive cell survival and plays an integral role in monocytic development. (Microbial infection) The TREX complex is essential for the export of Kaposi's sarcoma-associated herpesvirus (KSHV) intronless mRNAs and infectious virus production.
Synonyms: fSAP79; C22orf19; KIAA0983; PK1.3; Fmip
Tractability: PROTAC: UniProt records ubiquitination sites on it; ubiquitination databases record sites on it; its protein half-life has been measured.
Gene: Protein-coding gene on chromosome 22 (29,505,879 to 29,555,216, reverse strand). Ensembl gene ENSG00000100296.
Subcellular location: Nucleus; Cytoplasm
Subcellular location (Human Protein Atlas): Nucleoplasm
Pathways (Reactome):
Metabolism of RNA: Transport of Mature mRNA derived from an Intron-Containing Transcript; mRNA 3'-end processing
Immune System: Signaling by CSF1 (M-CSF) in myeloid cells
Gene Ontology:
Molecular function: protein binding; mRNA binding
Biological process: monocyte differentiation; mRNA export from nucleus; primitive hemopoiesis
Cellular component: chromosome, telomeric region; cytoplasm; nucleoplasm; nucleus; THO complex; THO complex part of transcription export complex; transcription export complex
Genetic constraint (gnomAD): Loss-of-function variants: 39 observed, 81.55 expected, observed/expected ratio (o/e) 0.48, 90% interval 0.37 to 0.62. The upper end of that interval is the gene's LOEUF score, 0.62, which puts it in group 2 of 6, group 1 being the genes least tolerant of losing a copy. Missense variants: 612 observed, 834.13 expected, observed/expected ratio (o/e) 0.73, 90% interval 0.69 to 0.78. Synonymous variants: 275 observed, 315.28 expected, observed/expected ratio (o/e) 0.87, 90% interval 0.79 to 0.96.
Homologues: Orthologues: macaque THOC5 (99% identical), chimpanzee THOC5 (99% identical), pig THOC5 (98% identical), dog THOC5 (98% identical), guinea pig THOC5 (97% identical), rat Thoc5 (96% identical), mouse Thoc5 (96% identical), rabbit THOC5 (95% identical), tropical clawed frog thoc5 (76% identical), zebrafish thoc5 (68% identical), Drosophila melanogaster thoc5 (26% identical), Caenorhabditis elegans thoc-5 (22% identical).
Diseases named in the same sentence as THOC5 in open-access papers:
THOC5 is named in the same sentence as 28 diseases in open-access papers, as found by Europe PMC text mining. Sharing a sentence is not in itself a finding about the gene and the disease. The quoted sentences say what the papers report.
breast carcinoma (4 papers, 2011 to 2025). "Studies in vitro have demonstrated that THOC5 is essential for the self-renewal of tumor stem cells, and the knockdown of THOC5 can reduce breast cancer stem-like traits and enhance the sensitivity of tumors to radiotherapy." (PMID 40901498, 2025). "We evaluated the expression of the components of the human THO complex, THOC1, THOC2, THOC3, THOC5, THOC6 and THOC7, as well as the expression levels of UAP56 and ALY in breast cancer cell lines." (PMID 21329510, 2011). "Besides, analysis of the Molecular Taxonomy of Breast Cancer International Consortium (METABRIC) dataset shows that the high intratumoral expression of THOC2 gene expression was remarkably associated with a worse prognosis in BC and TNBC patients, while THOC5 displayed no relevance to survival." (PMID 34708581, 2021).
hepatocellular carcinoma (2 papers, 2024 to 2025). A malignant tumor that arises from hepatocytes. "As THOC5 has been reported to be associated with lipid accumulation in hepatocellular carcinoma cells, it is reasonable to postulate that THOC5 participates in the biological regulation of lncBCL2L11 in GBC." (PMID 38519939, 2024). "Finally, our prognostic associations are based on retrospective datasets, and thus, prospective clinical studies are needed to validate THOC5 as a biomarker in hepatocellular carcinoma." (PMID 40901498, 2025).
anemia (1 paper, 2010). A reduction in the number of red blood cells, the amount of hemoglobin, and/or the volume of packed red blood cells. "As severe leukocytopenia and anemia were observed in THOC5/FMIP depleted mice, we examined the bone marrow cells after induced depletion of THOC5/FMIP protein." (PMID 20051105, 2010). "Although the liver looked pale in these mice, no abnormalities were observed and no cleaved caspase 3 positive cells were seen in this organ, suggesting that THOC5/FMIP depleted mice may have anemia, and/or internal bleeding." (PMID 20051105, 2010). "In addition, the erythrocyte count, hemoglobin and hematocrit levels went down to 2 to 4 × 106/mm3 (P = 0.01), 3-7 g/dl (P = 0.01), 13% (P = 0.01), respectively, suggesting that THOC5/FMIP depleted mice died from hematological disorders such as anemia, and internal bleeding." (PMID 20051105, 2010).
autism (1 paper, 2021). Persistent deficits in social interaction and communication and interaction as well as a markedly restricted repertoire of activity and interest as well as repetitive patterns of behavior. "To further determine whether these predicted proteins were associated with ASD, we compared their corresponding genes with autism-related genes listed in the AutismKB and found that 55 genes were reported associated with ASD except TTC13, RARS, THOC5, and ATPAF1." (PMID 33716802, 2021).
chronic myeloid leukemia (1 paper, 2016). "Phosphorylation of THOC5 on tyrosine 225 promotes its incorporation into mRNPs and THOC5 phosphorylation by leukemogenic protein tyrosine kinases is increased in patients with chronic myeloid leukemia." (PMID 27679854, 2016).
leukemia (1 paper, 2014). A malignant (clonal) hematologic disorder, involving hematopoietic stem cells and characterized by the presence of primitive or atypical myeloid or lymphoid cells in the bone marrow and the blood. "Thus, tyrosine phosphorylation of THOC5 may be involved in leukemic cell behavior, however the biological consequence of tyrosine phosphorylation of THOC5 during leukemia development remains to be studied." (PMID 24410813, 2014). "In addition, recent data imply the involvement of THOC5 in leukemia development." (PMID 24410813, 2014).
liver cancer (1 paper, 2025). An epithelial or non-epithelial malignant neoplasm that arises from the liver. "Single-cell sequencing further categorized liver cancer cells into six clusters, revealing that malignant cells exhibit higher THOC5 expression levels." (PMID 40901498, 2025). "Additionally, data have shown the pivotal role of THOC5 depletion in inducing apoptosis in certain cancer cells, such as liver cancer cells." (PMID 40901498, 2025).
lymphoma (1 paper, 2021). A malignant (clonal) proliferation of B- lymphocytes or T- lymphocytes which involves the lymph nodes, bone marrow and/or extranodal sites. "THOC5 couples macrophage colony‐stimulating factor receptor signaling and contributes to macrophage and monocyte differentiation, suggesting the potential roles in the development of lymphoma." (PMID 33749163, 2021).
prostate carcinoma (1 paper, 2021). A carcinoma that arises from epithelial cells of the prostate gland. "We also probed the blots with an antibody against the small GTPase RAB11, since this protein was identified in both HMGB1 and THOC5 interactomes in prostate cancer cells." (PMID 34572914, 2021). "THOC1, THOC2, THOC5 and THOC6, members of the THO subcomplex of TREX which participates in mRNA processing and transport of RNPs from nucleus to cytoplasm, are present in HMGB1 immunoprecipitates from ovary and prostate cancer cells." (PMID 34572914, 2021).
triple-negative breast carcinoma (1 paper, 2025). An invasive breast carcinoma which is negative for expression of estrogen receptor (ER), progesterone receptor (PR), and human epidermal growth factor receptor 2 (HER2). "A study on triple-negative breast cancer (TNBC) also supports this mechanism: it found that THOC2, dependent on THOC5, facilitates the export of SOX2 and NANOG transcripts, thereby enhancing stemness features and radioresistance." (PMID 40901498, 2025).
cancer (11 papers, 2013 to 2025). A tumor composed of atypical neoplastic, often pleomorphic cells that invade other tissues. "Somatic mutations of THOC5 were detected in various cancers, with missense mutations being the most frequent type." (PMID 40901498, 2025). "High levels of THOC5 expression are associated with increased tumor proliferation, metastasis, and poor prognosis in various cancers." (PMID 40901498, 2025). "Aberrant expression and/or splicing of DST (also known as BPAG1), TEAD1 and THOC5 are associated with neurological disorders and cancer." (PMID 37026480, 2023). "In tumors such as LIHC, LUAD, KIRC, and COAD, THOC5 shows a positive correlation with TMB, suggesting that THOC5 may contribute to genomic instability and the accumulation of mutations in these cancers." (PMID 40901498, 2025). "Furthermore, depleting THOC5 in liver and cervical cancer cells results in the downregulation of several genes linked to cancer progression." (PMID 40901498, 2025). "Additionally, we examined the association between THOC5 expression and patient survival, immune cell infiltration, immune-related markers, and mutational status using computer-based algorithms across diverse cancer cohorts." (PMID 40901498, 2025). "THOC5 expression exhibits significant variation in its correlation with TMB across different cancers." (PMID 40901498, 2025). "This study investigates THOC5 expression across various cancers, its role in prognosis, and its potential therapeutic implications, particularly in liver hepatocellular carcinoma (LIHC)." (PMID 40901498, 2025). "We analyzed THOC5 expression and its prognostic significance across various cancer types using globally available public datasets." (PMID 40901498, 2025). "THOC5 promotes the expression of oncogenes and supports cancer cell survival by influencing mRNA stability and export." (PMID 40901498, 2025). "We systematically analyzed the differential expression of THOC5 across multiple tumor types using integrated data from the cancer genome atlas (TCGA) and genotype-tissue expression (GTEx) cohorts." (PMID 40901498, 2025). "Results indicate that THOC5 is overexpressed in various cancers and correlates with unfavorable prognosis." (PMID 40901498, 2025). "We found that THOC5 exhibited distinct expression patterns across different tumors, suggesting a complex regulatory role in cancer." (PMID 40901498, 2025). "Due to its role in enhancing oncogenic signaling, THOC5 has become a potential target for cancer therapy, especially for cases that are resistant to treatment." (PMID 40901498, 2025). "LncBCl2L11 prevented the binding of THOC6 and THOC5 and causes the degradation of THOC5, thus promoting the accumulation of acylcarnitines in GBC cells, leading to the malignant progression of cancer cells." (PMID 38519939, 2024). "It is known that THO complex subunit 5 (THOC5, an mRNA export complex member) plays a key role in stem cell and cancer cell biology." (PMID 37596619, 2023). "Multiple TREX mRNA export complex subunits (e.g., THOC1, THOC2, THOC5, THOC6, THOC7) have now been implicated in neurodevelopmental disorders (NDDs), neurodegeneration and cancer." (PMID 32116545, 2020). "This study analyzed THOC5 expression patterns using integrated public pan-cancer data." (PMID 40901498, 2025). "THOC5 may promote cancer cell proliferation and help maintain genomic stability by regulating the cell cycle and DNA repair, which are crucial for tumor cells." (PMID 40901498, 2025). "More importantly, we show that THOC2 and THOC5 were upregulated in human TNBC tissues and significantly associated with a worse survival rate in TNBC patients, highlighting the therapeutic value and targetable advantage of the THOC in cancer." (PMID 34708581, 2021).
cancer (continued). "THOC5 is highly specialised in the processing of mRNAs related to cancer proliferation, since it contributes to more than 90% of the 3′ processing and/or export of immediate-early genes induced by growth factors and/or cytokines, but only to less than 1% of total mRNA export in the steady state." (PMID 34572914, 2021). "The data from these studies also suggest that THOC5 may be a useful tool for studying stem cell biology, for modifying the differentiation processes and for cancer therapy." (PMID 24410813, 2014). "Thus, THOC5 may contribute to the abnormal proliferation and metastasis of cancer cells by influencing these mechanisms." (PMID 40901498, 2025). "In cancer, overexpression of THOC5 may change its preference for specific target transcripts." (PMID 40901498, 2025). "Furthermore, in this study, the role of THOC5 in maintaining cancer stemness was also established." (PMID 34708581, 2021). "Furthermore, THOC5 is a substrate for several oncogenic tyrosine kinases, suggesting that THOC5 may be involved in cancer development." (PMID 24410813, 2014). "Furthermore, the knockdown of THOC1 or THOC5 did not cause apoptosis in normal cells, but it causes apoptosis in cancer cells." (PMID 24410813, 2014). "Further prognostic analysis showed that THOC5 negatively impacted OS, DSS, DFI, and PFI in various cancers." (PMID 40901498, 2025). "However, the role of THOC2 and THOC5 in regulating cancer stemness is not reported yet, and the underlying mechanism remains unclear." (PMID 34708581, 2021). "To address the clinical significance of THOC2 and THOC5 in TNBC, we also performed the survival analysis based on the cancer tissue IHC scoring in TMAs." (PMID 34708581, 2021). "THOC5 could be a prognostic biomarker and therapeutic target in LIHC and various cancers, providing alternative treatment options when immunotherapy fails." (PMID 40901498, 2025). "In total, 3,295 case of cancers and 2,690 non-tumor livers were included to evaluation the expression of THOC5." (PMID 40901498, 2025). "In the DNAss analysis, THOC5 expression demonstrated a negative or weak correlation with stemness in cancers such as THYM and LIHC." (PMID 40901498, 2025). "The THOC5 gene, part of the THO complex, has emerged as a potential regulator in cancer biology." (PMID 40901498, 2025).
tumor (3 papers, 2020 to 2025). "This indicates that elevated THOC5 expression is associated with immune checkpoint activation, crucial for tumor immune escape and significant in tumor immunotherapy." (PMID 40901498, 2025). "Correlation analysis of THOC2 and THOC5 expression with TMA clinicopathological variables shows that high expression of THOC2 was associated with larger tumor size (p = 0.029) and lymph node invasion (p = 0.027)." (PMID 34708581, 2021). "This indicates that THOC5 might promote genomic instability and mutation accumulation, driving tumor development." (PMID 40901498, 2025). "Recent advances in scientific research have increasingly highlighted the significance of THOC5 in tumor biology." (PMID 40901498, 2025). "Third, functional validation in vivo (e.g., xenograft or genetically engineered mouse models) will be important to confirm THOC5’s role in tumor progression and drug response." (PMID 40901498, 2025). "Our in-house sequencing data confirmed the increased expression of THOC5 in LIHC relative to non-tumor liver tissues." (PMID 40901498, 2025). "A previous work has indicated that THOC5 selectively exports transcripts involved in cell growth, differentiation, survival as well as tumor development." (PMID 40901498, 2025). "The findings revealed that the group with elevated THOC5 expression exhibited increased sensitivity to various conventional anti-tumor drugs." (PMID 40901498, 2025). "In LIHC, both THOC5 mRNA and protein was confirmed to be overexpressed in LIHC elevated THOC5 correlated with advanced tumor stages and poor survival outcomes." (PMID 40901498, 2025). "Furthermore, high THOC5 was also indicated to activate several tumor signaling pathways, such as EGFR, Hypoxia and MAPK pathways." (PMID 40901498, 2025). "Moreover, elevated THOC5 expression correlated with increased sensitivity to various anti-tumor drugs." (PMID 40901498, 2025). "These correlations indicate that THOC5 could significantly influence immune cell distribution and function in the tumor microenvironment." (PMID 40901498, 2025). "Moreover, 50% depletion of THOC5 in the HCC cell lines Huh7 and HepG2 induces apoptosis, and THOC5 expression is enhanced in 78% of cytological differentiation grading G2 and G3 tumor in primary HCC." (PMID 33411682, 2020). "THOC5 may influence immune cell distribution and function within the tumor microenvironment." (PMID 40901498, 2025). "Functional assays demonstrated that silencing THOC5 significantly reduced LIHC cell viability and suppressed key tumor behaviors, including cell proliferation, migration, and invasion." (PMID 40901498, 2025). "The global public datasets revealed significant overexpression of THOC5 mRNA in LIHC tissues, with a standardized mean difference (SMD) of 0.62 (95% CI 0.42–0.81), derived from 3,295 tumor and 2,959 non-tumor liver samples." (PMID 40901498, 2025). "Additionally, correlation analysis between THOC5 and MSI reveals significant positive correlations in COAD, LIHC, and KIRC, further suggesting a possible role in regulating tumor evolution and genomic instability." (PMID 40901498, 2025).
infection (2 papers, 2010 to 2022). The state of being infected such as from the introduction of a foreign agent such as serum, vaccine, antigenic substance or organism. "Four days after infection the downregulation of THOC5 was confirmed by THOC5-specific immunoblot." (PMID 36590164, 2022). "After infection with adenovirus carrying GFP and cre-recombinase, THOC5/FMIP was drastically reduced within four days." (PMID 20051105, 2010).
THOC5 also shares sentences with these, for which no sentence is quoted: bacterial infection (1 paper); cardiovascular diseases (1); colon adenocarcinoma (1); Depression (1); diabetes (1); gallbladder cancer (1); glioblastoma multiforme (1); glioma (1); hematological disorders (1); myeloproliferative disorder (1); neurodevelopmental disorder (1); neurological disorders (1); prostate adenocarcinoma (1); Sepsis (1); stomach adenocarcinoma (1).